RNU6-789P (RNA, U6 small nuclear 789, pseudogene)
Gene: Small nuclear RNA gene on chromosome 3 (136,721,394 to 136,721,495, reverse strand). Ensembl gene ENSG00000252914.
Homologues: Orthologues: chimpanzee U6 (98% identical), guinea pig U6 (64% identical), dog U6 (62% identical). Paralogues in human: RNU6-510P (77% identical), RNU6-589P (76% identical), RNU6-936P (76% identical), RNU6-354P (75% identical), RNU6-610P (75% identical), RNU6-188P (75% identical), RNU6-1131P (74% identical), RNU6-125P (74% identical), RNU6-128P (74% identical), RNU6-21P (74% identical), RNU6-251P (74% identical), RNU6-616P (74% identical), and 1285 more.